PLCXD1 (phosphatidylinositol specific phospholipase C X domain containing 1)
Synonyms: FLJ11323; LL0XNC01-136G2.1
Tractability: PROTAC: ubiquitination databases record sites on it.
Gene: Protein-coding gene on chromosome X (276,322 to 303,358, forward strand). Ensembl gene ENSG00000182378.
Subcellular location: Cytoplasm
Subcellular location (Human Protein Atlas): Cytosol
Gene Ontology:
Molecular function: phosphoric diester hydrolase activity
Biological process: lipid metabolic process
Cellular component: cytoplasm
Homologues: Orthologues: macaque PLCXD1 (94% identical), chimpanzee PLCXD1 (84% identical), rabbit PLCXD1 (73% identical), mouse Plcxd1 (68% identical), rat Plcxd1 (68% identical), tropical clawed frog plcxd1 (47% identical), zebrafish zgc:112023 (43% identical), Drosophila melanogaster CG10747 (28% identical), Caenorhabditis elegans F38E9.1 (25% identical). Paralogues in human: PLCXD2 (33% identical), PLCXD3 (31% identical).
Diseases named in the same sentence as PLCXD1 in open-access papers:
PLCXD1 is named in the same sentence as 5 diseases in open-access papers, as found by Europe PMC text mining. Sharing a sentence is not in itself a finding about the gene and the disease. The quoted sentences say what the papers report.
melanoma (2 papers, 2015 to 2016). A malignant, usually aggressive tumor composed of atypical, neoplastic melanocytes. "In a recent report attempting to identify tumor suppressors in malignant melanoma, PLCXD1 (Phosphatidylinositol-specific phospholipase C, X domain containing 1) was one of 7 genes to be methylated or deleted in all 14 melanoma tumor samples that were examined." (PMID 27655702, 2016). "This is contrary to the results reported in the only study available on PLCXD1 which showed growth-suppressive effects in melanoma cells." (PMID 25961594, 2015). "Additionally, when PLCXD1 was ectopically expressed, it reduced proliferation in 2 of the 4 melanoma cell lines that were assessed." (PMID 27655702, 2016). "The function of PLCXD1 is largely unknown although its over-expression suppresses melanoma cell growth, suggesting anti-oncogenic properties." (PMID 25961594, 2015).
PLCXD1 also shares sentences with these, for which no sentence is quoted: diabetes (1 paper); dyschondrosteosis (1); retinal vein occlusion (1); tumor (1).